VEGFA (vascular endothelial growth factor A)
Diseases named in the same sentence as VEGFA in open-access papers (continued):
Sharing a sentence is not in itself a finding about the gene and the disease.
cervical squamous cell carcinoma (14 papers, 2008 to 2025). A squamous cell carcinoma arising from the cervical epithelium. "VEGFA was validated an unfavorable molecules in HPV cervical squamous cell carcinoma." (PMID 36185274, 2022). "By using a qRT-PCR array, we identified CD3E, IL6, VEGFA and a high IL6/IL17 ratio combined with low IL5 expression as the most prognostic factors in squamous cervical cancer." (PMID 25889974, 2015).
cutaneous melanoma (14 papers, 1997 to 2025). A primary melanoma arising from atypical melanocytes in the skin. "A massive MΦ infiltration has been linked to angiogenesis in cutaneous melanoma, as the numbers of MΦs and neovascularization and vascular endothelial growth factor-A increased significantly with augmented tumor depth." (PMID 34831352, 2021). "Consequently, we validated our previous pilot study in a large and independent patient cohort, using standard FFPE tissue sections instead of cryosections, and confirmed the role of CCL20, TNF, and VEGFA expression by TAMs in predicting clinical behavior of primary cutaneous melanoma patients." (PMID 34439098, 2021).
Hydrocephalus (14 papers, 2015 to 2025). Hydrocephalus is an active distension of the ventricular system of the brain resulting from inadequate passage of CSF from its point of production within the cerebral ventricles to its point of absorption into the systemic circulation. "HBEGF also has an effect on angiogenesis, expression of vascular endothelial growth factor A (VEGF‐A), inflammation, and oxidative stress and has been implicated in hydrocephalus." (PMID 39046104, 2024).
lymphedema (14 papers, 2009 to 2025). Excess fluid collection in tissues, causing swelling. "Compared with the lymphedema and decellularized lymph node-scaffold groups, in which the number of VEGFA-expressing cells was low, the numbers of VEGFA-positive cells were significantly higher in the hADSCs injection and recellularized lymph node-scaffold groups." (PMID 37012287, 2023).
Kawasaki disease (13 papers, 2010 to 2025). A rare inflammatory disease characterized by an acute febrile, systemic, self-limiting, medium-vessel vasculitis primarily affecting children. "CYFIP2 (cytoplasmic FMR1-interacting protein 2) forms part of the VEGFA–VEGFR2 pathway and is associated in humans with susceptibility to Kawasaki disease and coronary artery lesions, interacting with PDE2A so that high-risk allele combinations account for 67% of cases in this human population." (PMID 31683933, 2019). "Furthermore, an overexpressed miR-93-5p negatively regulates vascular endothelial growth factor A (VEGF-A) production in circulating peripheral blood mononuclear cells (PBMCs) in patients with Kawasaki disease, thus contributing to the pathogenesis of coronary artery involvement." (PMID 40297582, 2025). "PBMCs from patients with Kawasaki disease expressed higher levels of VEGFA and HIF-1α than did PBMCs from healthy control patients after 24 hours of incubation with NETs from patients with Kawasaki disease." (PMID 40083688, 2025).
thymoma (13 papers, 2014 to 2025). A neoplasm arising from the epithelial cells of the thymus. "B3 thymomas and TC expressed significantly higher levels of both VEGFA and VEGFC compared to A, AB, and B1 thymomas." (PMID 38069386, 2023). "As lymphocytes express TNF‐α‐receptors I and II while not expressing receptors for IL‐5 or VEGFA, we tested whether the mouse lymphocyte derived BW5147 thymoma reporter cell line is sensitive to high concentrations of rhTNF‐α." (PMID 34842342, 2022).
thyroid (13 papers, 2010 to 2026). "Sufficient evidence indicates that VEGFA plays a complicated and critical role in thyroid disorder, and that VEGFA polymorphisms can contribute to the interindividual variants in VEGF expression." (PMID 28178662, 2017). "The relationship between VEGFA polymorphisms and thyroid diseases had been analyzed in many previous studies." (PMID 28178662, 2017). "The inconsistent reports on the role of VEGFA in thyroid disorders might be due to the effects of the different polymorphisms in this gene." (PMID 28178662, 2017). "Since the exact mechanism or roles of VEGFA SNPs on thyroid disease are still unknown, further studies with larger samples are needed to validate our findings." (PMID 28178662, 2017). "Most of the 16 thyroid-related genes, in addition to several cancer-related genes including AKT2, VEGFA, ERBB2, and CCND3, were positively correlated with TDS." (PMID 41353477, 2025).
tongue squamous cell carcinoma (13 papers, 2012 to 2023). A squamous cell carcinoma that arises from the tongue. "In one study, salivary levels of IL-1α, IL-6, IL-8, vascular endothelial growth factor A (VEGF-a) and TNF-α were able to predict the progression of tongue SCC from high-risk to neoplasm, serving as potential biomarkers for cancer screening and early detection." (PMID 26082902, 2015).
urothelial carcinoma (13 papers, 2012 to 2024). A malignant neoplasm derived from the transitional epithelium of the urinary tract (urinary bladder, ureter, urethra, or renal pelvis). "The prognostic importance of VEGFA in urothelial carcinoma has already been implicated in a several studies." (PMID 22895562, 2012). "Background and Purpose: This research aimed to excavate the alternative mechanism of CEBPD on tumor growth and explore the biological significance of the CEBPD/hsa-miR-429/VEGFA axis on angiogenesis in urothelial carcinoma (UC)." (PMID 35203290, 2022). "Based on the expression of SDC1, LUM, VEGFA, TIMP3 and WNT7B in various urothelial carcinoma cell lines in the CCL database, we selected J82 and UMUC3 as the verification cell lines, and marked them with puromycin resistance labelling." (PMID 38183115, 2024).
Uterine leiomyoma (13 papers, 2010 to 2026). The presence of a leiomyoma of the uterus. "Using MCODE, we found that STAT3, VEGFA, CCND1, and other genes were the hub genes of uterine leiomyoma, proving that they might play a significant role in the pathogenesis and progression uterine leiomyoma." (PMID 35113040, 2022).
alopecia (12 papers, 2007 to 2025). Hair loss usually from the scalp. "Furthermore, DPC-derived exosomes have been shown to significantly enhance wound healing through KLF4/VEGFA-driven angiogenesis, which could play a crucial role in the Mogadishu effective treatment of hair loss with DPC-derived exosomes." (PMID 39065633, 2024).
amyloid (12 papers, 2013 to 2025).
anaplastic thyroid cancer (12 papers, 2016 to 2025). "In addition, high FOXK2 expression activates VEGFA, leading to anaplastic thyroid cancer via the VEGFA/VEGFR1 pathway." (PMID 39552461, 2024).
basal cell carcinoma (12 papers, 2014 to 2024). A carcinoma involving the basal cells. "Vascular endothelial growth factor A (VEGF-A) and interleukin-6 (IL-6) expressions in basal cell carcinoma (BCC) punch biopsy samples from head and neck." (PMID 37902813, 2023).
co-infection (12 papers, 2008 to 2025). "Specifically, production of key proinflammatory cytokines (e.g., IL-1α and IL-1β), chemokines (e.g., CCL20 and CXCL8), and VEGFA was markedly downregulated during co-infection with either HCMV variant, reflecting the known synergistic interference between the two pathogens." (PMID 40980889, 2025). "maxima co-infection compared with uninfected controls (ANXA1, HSP90B1, VEGFA, MTTP, TNFSF11B, TCF12, APP, and CXCL14)." (PMID 25504150, 2014).
hemangioblastoma (12 papers, 2011 to 2024). "CXCR4, CXCL12, and VEGFA were all overexpressed in hemangioblastomas as compared to normal surrounding tissue." (PMID 26920352, 2016). "Compared to normal surrounding tissue CXCR4, CXCL12, and VEGFA were overexpressed in hemangioblastomas." (PMID 26920352, 2016). "We also found VEGFA overexpressed in stromal hemangioblastoma cells as compared to normal surrounding brain tissue." (PMID 26920352, 2016). "This study shows that CXCR4, CXCL12, and VEGFA are all overexpressed in stromal hemangioblastoma cells compared to normal surrounding brain tissue." (PMID 26920352, 2016). "This is the first study in which expression of CXCR4, CXCL12, and VEGFA is compared in both sporadic and VHL associated hemangioblastoma patients." (PMID 26920352, 2016). "The finding that CXCR4 expression was higher in sporadic hemangioblastomas is striking as in VHL-disease a germline mutation in VHL leads to a defect VHL protein which results in enhanced transcription of CXCR4, its ligand CXCL12 as well as VEGFA." (PMID 26920352, 2016). "We aimed to determine in VHL-related and sporadic hemangioblastomas CXCR4, CXCL12, and VEGFA protein expression and to correlate this to hemangioblastoma size and expression in normal surrounding tissue." (PMID 26920352, 2016). "VEGFA was expressed higher than normal in sporadic and VHL-related hemangioblastomas, and present in stromal hemangioblastoma cells and vascular endothelial cells." (PMID 26920352, 2016). "Hemangioblastomas overexpress CXCR4, CXCL12, and VEGFA compared to normal surrounding tissue." (PMID 26920352, 2016). "For VHL-related hemangioblastoma, targeted therapy against CXCR4 and VEGFA could potentially be combined with conventional therapy as VHL-related disease is multiple and lesions often reoccur after surgery." (PMID 26920352, 2016). "Earlier studies in VHL related hemangioblastoma found upregulated CXCR4, CXCL12, and VEGFA." (PMID 26920352, 2016). "Therefore, the aim of this study was to investigate CXCR4, CXCL12, and VEGFA protein expression in VHL-related and sporadic hemangioblastomas and to correlate this to size as measured by MRI before surgery to investigate possible differences between VHL-related and sporadic hemangioblastoma." (PMID 26920352, 2016).
hepatoblastoma (12 papers, 2013 to 2024). Hepatoblastoma (HB) is a malignant hepatic tumor and is the most common pediatric liver cancer. "Further investigation unveiled that CRNDE regulates hepatoblastoma angiogenesis by targeting the MiR-203/VEGFA axis." (PMID 38390281, 2024). "A recent study reported that TUG1/miR-34a-5p/VEGFA network was involved in regulating hypervascularity and hepatoblastoma progression." (PMID 29228631, 2017). "ELISA assays showed that CRNDE knockdown significantly decreased VEGFA and Ang-2 levels in the hepatoblastoma tissue." (PMID 28178668, 2017). "Western blots and enzyme-linked immunosorbent assay (ELISA) experiments showed that TUG1 knockdown significantly decreased VEGFA levels in hepatoblastoma tissue and blood." (PMID 27362796, 2016). "Taken together, the angiogenic activity in CM of hepatoblastoma cells was primarily due to VEGFA production." (PMID 27362796, 2016). "TUG1, miR-34a-5p, and VEGFA constitutes to a regulatory network, and participates in regulating hepatoblastoma cell function, tumor progression, and tumor angiogenesis." (PMID 27362796, 2016). "TUG1/miR-34a-5p/VEGFA network is involved in regulating hypervascularity and hepatoblastoma progression." (PMID 27362796, 2016). "TUG1 upregulation contributes to the hypervascularity of hepatoblastoma via VEGFA induction." (PMID 27362796, 2016). "TUG1/miR-34a-5p/VEGFA network may become a candidate target for hepatoblastoma therapy." (PMID 27362796, 2016). "Once lncRNA-TUG1 is significantly upregulated during hepatoblastoma progression, TUG1 upregulation could alleviate miR-34a-5p repressive effect, resulting in a significant increase in the expression of VEGFA, a target gene of miR-34a-5p." (PMID 27362796, 2016).
kidney tumor (12 papers, 2007 to 2025). "High miR-106a-5p levels can decrease VEGFA levels and especially kill kidney tumor cells." (PMID 33224312, 2020). "Our finding revealed that miR-106a-5p can decrease VEGFA protein expression significantly; thus, we try to find out whether miR-106a-5p can specially kills kidney tumor cells." (PMID 33224312, 2020). "Our finding demonstrates that miR-106a-5p can represent a potential biomarker for ccRCC patients and increased miR-106a-5p levels can dramatically decrease the protein level of VEGFA in kidney tumor cells, consequently inhibiting tumor cell proliferation and leading to cell death." (PMID 33224312, 2020).
knee osteoarthritis (12 papers, 2014 to 2026). "In our previous research, the expression levels of VEGFA have significantly increased in knee osteoarthritis synovial membranes." (PMID 32840301, 2020).
varicocele (12 papers, 2016 to 2026). A condition characterized by the dilated tortuous veins of the spermatic cord with a marked left-sided predominance. "In fact, in experimental varicocele, PDRN induced Vascular Endothelial Growth Factor-A (VEGF-A) production, thus promoting intratesticular vascularization and improving spermatogenesis." (PMID 28119612, 2016).
ankylosing spondylitis (11 papers, 2009 to 2025). An autoimmune chronic inflammatory disorder characterized by inflammation in the vertebral joints of the spine and sacroiliac joints. "It was already shown that VEGFA serum and synovial fluid levels are elevated in patients with ankylosing spondylitis expressing features of peripheral arthritis." (PMID 33958655, 2021).
corneal diseases (11 papers, 2009 to 2025). "Corneal disease is characterized by loss of corneal immunologic privilege and extensive neovascularization driven by vascular endothelial growth factor-A (VEGF-A)." (PMID 21998580, 2011).
disc degeneration (11 papers, 2018 to 2026). "In conclusion, constant compression caused degeneration of the vertebral endplate and decreased vascular buds in the endplate, thereby accelerating disc degeneration; VEGFA is involved in this process." (PMID 32584845, 2020). "The findings indicated that HIF-2α, CAIX, PPP1R15A, VEGFA, and EGLN3 could potentially serve as new indicators of disc degeneration." (PMID 38254196, 2024). "Measuring the target index, HIF-2α, CAIX, PPP1R15A, VEGFA, and EGLN3 could potentially serve as new indicators for disc degeneration." (PMID 38254196, 2024).
erectile dysfunction (11 papers, 2010 to 2024). Persistent or recurrent inability to achieve or to maintain an erection during sexual activity. "There was an associated overexpression of eNOS and VEGFa, suggesting that miR‐423‐5p may be potentially used as a target in cell therapy for DM associated erectile dysfunction." (PMID 34545676, 2021).
gastritis (11 papers, 2011 to 2025). Inflammation of the stomach. "VEGFA and iNOS levels are also high in patients with chronic atrophic gastritis as well as in metaplastic and dysplastic areas." (PMID 36874142, 2023).
gestational diabetes (11 papers, 2013 to 2025). Carbohydrate intolerance first diagnosed during pregnancy. "Mothers with gestational diabetes mellitus show a down-regulation of vascular endothelial growth factor A (VEGFA), which has a critical role in angiogenesis, producing an abnormal coiling pattern of the umbilical cord." (PMID 36556956, 2022). "The expression of both VEGFA and KDR was reduced in gestational diabetes mellitus pregnancies compared to normal pregnancies." (PMID 38304230, 2023).
gout (11 papers, 2013 to 2024). A condition characterized by painful swelling of the joints, which is caused by deposition of urate crystals. "For further assessment on a protein level, serum TGF-β-LAP and two downstream targets LIF and VEGFA levels were determined in the same individuals with normouricemia, hyperuricemia and gout." (PMID 36850003, 2023). "Six significantly distinct proteins were identified in the serum proteomic profile of gout flares, these patients having elevated circulating concentrations of MMP-1, IL-6, VEGFA, and CCL23 and decreased DNER (Delta and Notch-like epidermal growth factor-related receptor) and CD6 levels." (PMID 37810213, 2023). "In a previous report investigating TGF-β in urate-induced inflammatory priming, we were not able to observe major differences in TGF-β or VEGFA levels during gout flares compared to inter-critical patients with gout." (PMID 37810213, 2023).
chorioamnionitis (10 papers, 2012 to 2025). A morphologic finding indicating inflammation of the fetal sac membranes. "The VEGFA protein has been found to be elevated in the decidual cells of women with intra-amniotic infection, which is a major cause of SPB." (PMID 22496790, 2012).
chronic lung disease (10 papers, 2012 to 2024). According to the definitions of the American and British Thoracic Societies, including pulmonary functional tests, X-rays, and CT scans for items such as fibrosis, bronchiectasis, bullae, emphysema, nodular or lymphomatous abnormalities. "In accordance with our results, previous studies have reported that reduced expression of VEGFA is associated with acute and chronic lung disease." (PMID 35337337, 2022).
cutaneous squamous cell carcinoma (10 papers, 2011 to 2025). "Studies have demonstrated that miR-361-5p plays a role in cutaneous squamous cell carcinoma by targeting vascular endothelial growth factor A (VEGFA), whereby suppression of this miRNA can inhibit the malignant behaviors of the cancer cells." (PMID 41462601, 2025). "In cutaneous squamous cell carcinoma, NRP1 is expressed in highly differentiated tumors, suggesting that it could function as a reservoir to sequester VEGFA to the epithelial compartment, thereby limiting its bioactivity 39, reducing angiogenesis and tumor progression." (PMID 30027561, 2018).
ependymoma (10 papers, 2010 to 2024). A WHO grade II, slow growing tumor of children and young adults, usually located intraventricularly. "Only one of three patients benefited from tier 5 PGT: a patient with ependymoma (EPN) with high vascular endothelial growth factor A (VEGFA) RNA expression with PR to bevacizumab." (PMID 38844796, 2024).
Lipedema (10 papers, 2020 to 2025). Disorder of adipose tissue characterized by symmetric and bilateral enlargement of the lower extremities due to abnormal deposition of subcutaneous fat often in obese women. "On the other hand, VEGFA, a lymphatic-related cytokine was among the inflammatory markers, upregulated in lipedema, and has also been related to lipedema progression." (PMID 39590304, 2024). "For instance, the cytokines VEGFA, TGFα and TGFβ1 were among the inflammatory markers upregulated in lipedema." (PMID 36387874, 2022). "With regard to other cytokines, the expression level of VEGFR-3 has been found to increase with the decreased expression of vascular endothelial growth factor A (VEGF-A) and vascular endothelial growth factor D (VEGF-D) in the AT of lipedema patients." (PMID 36551837, 2022).
meningitis (10 papers, 2010 to 2025). A disorder characterized by acute inflammation of the meninges of the brain and/or spinal cord. "Our observations reported here directly support the involvement of VEGFA and Snail-1 in meningitic E. coli induced BBB disruption, and VEGFA and Snail-1 would therefore represent the essential host targets for future prevention of clinical E. coli meningitis." (PMID 27588479, 2016).
non-alcoholic fatty liver disease (10 papers, 2017 to 2025). "In non-alcoholic fatty liver disease, hsa-miR-330 has been reported to modulate focal adhesion by targeting VEGFA and CDC42." (PMID 28570571, 2017). "Furthermore, KEGG analysis indicated that VEGFA was involved in biological activities such as thermogenesis, nonalcoholic fatty liver disease and oxidative phosphorylation." (PMID 36729917, 2023).